NF2 (NF2, moesin-ezrin-radixin like (MERLIN) tumor suppressor)
Diseases named in the same sentence as NF2 in open-access papers (continued):
Sharing a sentence is not in itself a finding about the gene and the disease.
tumor (continued). "Among NF2-deficient tumours, different histological subtypes have been found, indicating the presence of additional genetic features that might stratify NF2-deficient tumours into subgroups." (PMID 40562609, 2025). "The PI3K/mechanistic target of rapamycin kinase (mTOR) signaling pathway is also affected by genetic mutations in both NF1 and NF2, with its aberrant activation driving cell growth, proliferation, and survival, thereby playing a pivotal role in tumor development." (PMID 41359105, 2025). "Importantly, at the therapeutic level, our findings establish that targeting de novo pyrimidine synthesis elicits synthetic lethality in NF2-deficient PM, effectively suppressing tumor growth across multiple preclinical models." (PMID 40707702, 2025). "YAP/TAZ depletion in Nf2-deficient mice, furthermore, represses tumor formation." (PMID 39123485, 2024). "Variant allele frequency (VAF) of NF2 mutations ranged from 52 to 93% with significantly higher frequencies in tumors of patients with NF2 compared to patients in whom the mutation was only found in the tumor (p = 8.3e–08)." (PMID 38265489, 2024). "Thus, the zebrafish serves as a non-mammalian vertebrate organism that represents a cost-effective model to study the effects of loss of genes like NF2 on tumor formation." (PMID 39415595, 2024). "Whole genome and transcriptome sequencing of mucinous tubular and spindle cell RCC carcinomas (a rare cancer type) also revealed correlations between loss of Hippo pathway tumor suppressor genes such as NF2 and SAV1 and YAP1 nuclear accumulation during cancer progression." (PMID 39123485, 2024). "This means that cooccurring mutations in NF2 with CDKN2A/B may have synergistic effects on tumor incidence and malignancy." (PMID 38879686, 2024). "Furthermore, specific tumor characteristics, such as intratumoral calcification and the “en plaque” growth pattern, were identified as vital factors for predicting NF-2 copy number loss." (PMID 38611661, 2024). "In a prospective multicenter Phase II study, maintenance therapy with bevacizumab (5 mg/kg every 3 weeks) showed promising efficacy in preserving hearing and stabilizing tumor growth over 18 months in individuals with NF2-related SWN and hearing loss due to VSs." (PMID 39618887, 2024). "This inevitably omits potentially relevant variables for predicting post-surgical VS incidents, such as the presence of NF2 mutation status, tumor size or location, or surgical approaches, which could all impact the outcome of treatment." (PMID 39728082, 2024). "This case was considered “NF2 mutation detected in tumor” for all following analyses." (PMID 38265489, 2024). "Notably, several recent studies have explored the metabolic and immunological features associated with NF2, offering potential insights into tumor biology and the development of innovative therapeutic strategies." (PMID 38879686, 2024). "Glutamine supplementation and specific inhibition of glutamine transporters may inhibit NF2-associated tumor cells both metabolically and immunologically, which deserves subsequent investigation." (PMID 38879686, 2024). "For NF2-associated VS resistant to radiotherapy, targeted therapy such as bevacizumab has been shown to cause 30-60% tumor shrinkage and 20% hearing improvement, although it has several side effects, such as apparent drug resistance and rebound tumor progression." (PMID 38879686, 2024). "Moreover, the inherent tumor susceptibility of NF2 patients has been linked to a 6% increased risk of malignant transformation or new tumor growth on the irradiated tissues." (PMID 38672561, 2024). "Furthermore, specific tumor characteristics, such as intratumoral calcification and the “en plaque” growth pattern, emerged as vital predictors of NF-2 copy number loss." (PMID 38611661, 2024). "Therefore, a proposed mechanism for the loss of tumor suppressor activity in NF2-mutated sporadic meningiomas is through a loss of E-Cadherin activity." (PMID 39796693, 2024).
tumor (continued). "NF2 has been implicated in several pathways that enable its role as a tumor suppressor." (PMID 39796693, 2024). "Genomic studies have revealed mutations in genes such as SETD2, CDKN2A, SMARCB1, and NF2, which may contribute to the tumor's aggressive phenotype." (PMID 39310439, 2024). "NF2 is a well-known tumor suppressor, with high-frequency mutations in its FERM domain." (PMID 38710747, 2024). "We excluded from further consideration any gene that causes increased proliferation of NF2-WT cells, since these are potentially tumor suppressors and could lead to tumors if targeted pharmacologically in patients." (PMID 38879607, 2024). "We also confirmed loss of 14q across all grades in two patients whose tumours were NF2 mutant." (PMID 36882706, 2023). "Therefore, to predict tumor growth rate, it is necessary to evaluate factors other than germline variants of the NF2 gene from peripheral blood." (PMID 37087513, 2023). "However, especially in tumor susceptibility syndromes, such as NF2, there is a risk of malignant transformation of irradiated benign tumors and the development of new neoplasms in tissues surrounding the irradiated tumor." (PMID 36975476, 2023). "When the NF2 tumor suppressor locus is mutated, it often results in neuronal tumors." (PMID 37444578, 2023). "Of note, objective tumor responses were seen in 5/6 patients with tumors harboring NF2 mutations." (PMID 36917021, 2023). "In addition, in our cohort, tumours with NF2 mutations were strongly associated with losses on chromosome 10 and CNAs on 2p, 3p and 4p." (PMID 36882706, 2023). "Within the scope of PM, the increase in context‐dependent YAP/TAZ activation on NF2 loss likely translates to a decreased sensitivity to and enhanced proliferative potential within, a tumour niche, with a concurrently increased capacity for anchorage‐independent growth." (PMID 36740402, 2023). "Moreover, deletion of Rac1 was shown to block tumor initiation but paradoxically exacerbate hepatomegaly induced by Nf2 loss." (PMID 37174657, 2023). "In one patient, three different NF2 mutations were identified in four tumours." (PMID 36882706, 2023). "However, it would be necessary to consider factors in addition to NF2 germline P/LP variants to predict phenotypic characteristics such as tumor growth and hearing deterioration." (PMID 37087513, 2023). "In patients B, C and E an NF2 mutation was present in all tumours (pre- and post-progression)." (PMID 36882706, 2023). "Studies have reported that NF2 mutation is sufficient to induce tumor initiation and growth." (PMID 37080959, 2023). "Moreover, this describe the MRI features and the diagnostic accuracy for the tumours occurring in NF2 in detail." (PMID 36950434, 2023). "Especially in a tumor-predisposing syndrome like NF2, a reduction of the radiation dose could be important as patients are genetically prone to malignant transformation of irradiated tumors or the occurrence of new primary tumors." (PMID 36975476, 2023). "Tumours with NF2 mutations (patients B, C, E and G) had the most similar pattern of CNAs." (PMID 36882706, 2023). "As assessed using TMA analyses of human GC tissues, histologically high-grade tumor cells showed significantly lower NF2 expression than did low-grade tumor cells, implying that NF2 loss might be associated with tumor cell differentiation." (PMID 37730636, 2023). "A pathogenic NF2 mutation was detected in at least one tumour in four (40%) patients (B, C, E, G)." (PMID 36882706, 2023). "For some of these tumor, a sixth somatic hit was also seen in NF2 in the remaining 22q allele." (PMID 35723634, 2022). "Asbestos-exposed mice with heterozygous deletions of Cdkn2a, Nf2, and Bap1 have each been shown to have an increased risk of MMe development compared to wildtype mice, supporting the importance of these tumor suppressor genes as drivers in MMe pathogenesis." (PMID 35804881, 2022).
tumor (continued). "However, only one tumor in each patient was removed, which were all belonged to the NF2 mutation group." (PMID 36267986, 2022). "Inactivating mutations in the NF2 gene have been described in up to 75% of sporadic tumours." (PMID 35397067, 2022). "Neurofibromatosis type 2 (NF2) is a tumour predisposition syndrome with the autosomal-dominant transmission, complete penetrance, and variable phenotypic expression caused by germline alterations in the tumour suppressor gene NF21–3." (PMID 35681071, 2022). "Besides, loss of Nf2, a Hippo pathway tumor suppressor, results in increased expression of Notch2 in cholangiocytes." (PMID 35508987, 2022). "Addressing this pathophysiological question, the present study probed the connotation of driver gene mutation status in association with tumour location and revealed that the clinical significance of the NF2 mutation or 22q loss differed remarkably or inversely with tumour location." (PMID 35570314, 2022). "NF2 has an estimated incidence of 1:60 000 and is also an autosomal dominant condition arising from variants in the NF2 gene, located on chromosome 22, resulting in reduced production of the protein schwannomin which acts as a tumour suppressor." (PMID 35698239, 2022). "The loss of the NF2 mutation in the process of malignant transformation might also indicate that two different tumor clones were present at the first surgery." (PMID 34816314, 2022). "Furthermore, observed mosaicism of an identical NF2 rare missense variant in two tumor samples, or at low frequency in blood, would be strong evidence for pathogenicity of the variant in the absence of other variant identification." (PMID 35332608, 2022). "Clinical trials have focused on drugs that may block directly or indirectly pathways that are overactivated by NF1 or NF2 tumor-suppressor mutations." (PMID 35291225, 2022). "Malignant mutations related to the NF2/YAP signaling pathway could also express related neoantigens on tumor cells." (PMID 34123855, 2021). "correlated the vessel cross-sectional area (VA) and vessel density (VD) with tumor dimensions and tumor growth rate in both NF2-associated VS and sporadic VS, and found a positive correlation between VD and tumor growth rate in NF2-VS, and VA and VD with tumor size in sporadic VS." (PMID 34646772, 2021). "Neurofibromatosis type 2 (NF2) is a multiple neoplasia predisposing syndrome characterized by the formation of multiple nonmalignant nervous system tumors throughout the lifetime due to mutation in the NF2 tumor suppressor gene." (PMID 33604573, 2021). "Based on the data presented here, brigatinib possesses potent anti-tumor activity against NF2-deficient tumors via inhibition of multiple RTKs frequently activated in these tumors as well as blockade of several non-RTKs and serine-threonine kinases, but not ALK." (PMID 34264955, 2021). "The molecular mechanisms underlying contact inhibition remain unclear but Merlin, the protein encoded by the NF2 tumour suppressor gene is known to be an important mediator." (PMID 34424918, 2021). "Loss of heterozygosity of NF2 is required for tumor development, in keeping with its known tumor suppressor function, but other cooperating mutations may be necessary." (PMID 34885143, 2021). "For example, it has been estimated that about 14% of individuals with this syndrome carry a ring 22 chromosome (r22) and a recent study reports that 16% of subjects with r22 either received a diagnosis of Neurofibromatosis 2 (NF2) or had an NF2-associated tumor." (PMID 34440366, 2021). "The most frequent in MPM pathogenesis are genetic mutations in tumor suppressor genes (including neurofibromin 2 (NF2, merlin), cyclin-dependent kinase inhibitor 2A (CDKN2A), which shares a locus for both p16/INK4 and p14/ARF, and BRCA-associated protein-1 (BAP-1)." (PMID 34361048, 2021).
tumor (continued). "Therefore, in the future, it would apply the iron-chelating agents and antioxidants or SystemXC-inhibitors and GPXS inhibitors to regulate ferroptosis of tumor cells for malignant mutations related to the NF2/YAP signaling pathway." (PMID 34123855, 2021). "PTEN and NF2 are well-known cell-cycle regulators, frequently mutated in a wide range of neoplasms." (PMID 34884287, 2021). "With regard to the tumour, this contained a pathogenic somatic neurofibromatosis 2 (NF2) frameshift mutation and pathogenic loss of function somatic BAP1 mutation, which is in line with the immunohistochemistry result showing loss of nuclear labelling for BAP1." (PMID 34948918, 2021). "Therefore, we investigated the presence of the variant in the fresh tumor sample used to establish MPM_83 by sequencing multiple sections of this sample and found the NF2 variant at different frequencies, confirming the subclonal status of the NF2 mutation." (PMID 34261524, 2021). "These mutations were mutually exclusive and only one tumor harbored NF2 and AKT1 mutations." (PMID 33772057, 2021). "The finding of one tumour with deleterious NF2 mutation in its sarcomatoid component only, suggest that Hippo pathway mutations might be late events in ccRCCs with sarcomatoid dedifferentiation." (PMID 31959902, 2020). "There is a 2–9% risk of tumor regrowth for sporadic tumors and 12.5% for NF2-associated tumors." (PMID 31936793, 2020). "The median number of mutations per tumor besides NF2 was 1 (range 0–5)." (PMID 32724039, 2020). "Moreover, an NF2 mutation at a high allelic frequency (28.7%) was detected in the CSF from a patient bearing a very aggressive tumor (M17)." (PMID 32642718, 2020). "TERT_prom and NF2 mutations were significantly associated with the tumor stage (P = 0.025 and P = 0.007, respectively) and showed significant higher mutation rate in patients with stage IV tumors (20% and 28%, respectively) than in patients with stage I/III tumors (9% and 13%, respectively)." (PMID 32083805, 2020). "In 5% of the VS cases the cause is neurofibromatosis type 2 (NF2) and the tumor occurs bilaterally." (PMID 32244314, 2020). "However, further functional studies are needed to explore the role of NF2 loss in tumor dissemination." (PMID 33087175, 2020). "Chromosomal instability, which could be elevated by NF2 haploinsufficiency and further increased by loss of the second copy of NF2, is likely a predominant route of tumor evolution." (PMID 32724039, 2020). "Merlin, a tumor suppressor, is constantly inactivated in NF2-associated VSs." (PMID 32733557, 2020). "Implications of NF2 mutations significantly influencing meningioma progression have prompted clinical trial investigations of inhibition of focal adhesion kinase, thought to be associated with NF2/merlin-mediated tumor growth." (PMID 31191822, 2019). "Tumor volume may have also mediated the increased vasogenic edema observed in tumors with NF2 mutation." (PMID 31191822, 2019). "We identified novel mutations in non-NF2 skull base tumors that may be related to tumor prognosis including Fibroblast growth receptor-3 (FGFR3)." (PMID 31565188, 2019). "NF2-associated VSs exhibited excellent tumor control (10-year cumulative rate, 92% vs. 92% in sporadic VSs; p = 0.945) and worse overall survival (73% vs. 97%; p = 0.005), mainly due to tumor progression other than the treated VSs." (PMID 31591325, 2019). "However, the median tumor volume for NF2-associated tumors was 0.82 ccm, which is considerably smaller than in many existing publications." (PMID 31938667, 2019). "Most investigators have therefore relied upon established cell lines for xenograft experiments, such as the well-characterized BenMen1 line derived from a WHO grade I meningothelial meningioma which recapitulates key histologic and genetic features of the parent tumor, including NF2 mutation." (PMID 31652973, 2019).
tumor (continued). "Using this information, a rational hypothesis might be that CYC116 or danusertib could be effective and selective for NF2-deficient tumor cells; to our knowledge, the use of these molecules in this setting has yet not been explored." (PMID 30128806, 2018). "In addition to its value as a treatment modality, effective chemoprevention would provide a rationale for diagnosing individuals at known genetic risk for NF2 prior to tumor initiation." (PMID 29416648, 2018). "To assess whether COX-2 was overexpressed in the setting of Nf2-deficient tumor-forming tissue, we examined protein levels of COX-2 in the trigeminal ganglia of 6-month-old mice." (PMID 29416648, 2018). "The average allelic fraction of NF2 alterations was 57% (range 19–84%), in comparison with the cohort-wide average of 25% among all other mutations (p = 3.7 × 10−6), suggesting that NF2 mutations tend to be shared by a larger fraction of cells in the tumor relative to other mutations." (PMID 28713588, 2017). "In this subgroup of tumours, the inactivation of only one NF2 allele may be sufficient to promote the proliferation of the cells with biallelic SMARCB1 inactivation." (PMID 27921248, 2017). "Therefore, the association of tumour behaviours with the differential NF2 gene status, i.e., the ‘two-hits’ or the ‘one-hit’, seemed to be established through our comparisons of the clinical and genetic characteristics between the young and elderly patients." (PMID 28710469, 2017). "Additionally, positive dosage results were demonstrated in tumours in another three regions on chromosome 22, suggesting that the allelic loss of the NF2 gene occurred in conjunction with a loss of heterozygosity (LOH) event." (PMID 28710469, 2017). "However, genomic disruption tends to occur earlier in tumor evolution than do most mutations, and in one case, we observed three distinct NF2 alterations across multiple recurrences in the setting of an identical copy number profile." (PMID 28713588, 2017). "However, comprehensive mutation testing of LZTR1, SMARCB1, and NF2 using DNA derived from blood and different tumour samples of the patient is the method of choice to distinguish between the two conditions." (PMID 27921248, 2017). "Moreover, NF2 is commonly mutated in familial meningiomas and schwannomas as well as in spontaneous tumors of these and other tumor types." (PMID 27144834, 2016). "Furthermore, the occurrence of SETD2 (3p21) mutation was significantly higher in the NF2 loss than in the remaining uRCC tumours (44% versus 9%, Fisher's exact test, P=0.004)." (PMID 27713405, 2016). "Loss of the tumor suppressors NF2 and LATS2 have both been described in pleural mesotheliomas." (PMID 25798586, 2015). "However, the frequency of NF2 mutations is similar in all pathological tumor stages, suggesting that NF2 is important for tumor initiation but not critical for malignant progression." (PMID 25596744, 2015). "Therefore, both Nf2 isoforms must be considered as genuine tumour suppressors, considering heterozygous Nf2 deletion causes the development of multiple tumours within one year." (PMID 26258444, 2015). "On the basis of the statistical results and functional criteria, we filtered the data from 34 samples with unknown NF2 genotype (30 blood DNAs and 4 tumor DNAs) to identify causative alterations." (PMID 26066488, 2015). "In line with this hypothesis, mice which are heterozygous for NF2 mutations more frequently develop metastatic tumors, and both in vivo and in vitro re-expression of wild type merlin leads to reduced tumor growth and decreased cell motility." (PMID 25965831, 2015). "In addition, a distinct NF2 point mutation in each tumor was identified, representing independent second hits." (PMID 25739810, 2015). "However, recent population studies suggest that up to 1 in 300 people will develop a tumor with an underlying sporadic NF2 mutation during their lifetime." (PMID 25012216, 2014).